CDX2 (caudal type homeobox 2)
Diseases named in the same sentence as CDX2 in open-access papers (continued):
Sharing a sentence is not in itself a finding about the gene and the disease.
Barrett esophagus (29 papers, 2009 to 2025). Esophageal lesion lined with columnar metaplastic epithelium which is flat or villiform. "Ectopic expression of the intestine‐specific homeobox transcription factor CDX2 cause Barrett's esophagus and gastric‐intestinal metaplasia (Joo, Park, & Chun, 2016)." (PMID 31090196, 2019). "In the mouse intestine, loss of Cdx2 leads to the formation of a squamous epithelium that resembles the esophagus, whereas, in Barrett's esophagus, Cdx2 is ectopically expressed in metaplastic cells." (PMID 27112333, 2016). "On the other hand there is also evidence showing that activated BMP pathway associated with CDX2 expression in different models of esophagitis and Barrett's esophagus." (PMID 25365201, 2014). "The CDX1 and CDX2 expression promotes the transdifferentiation of the normal squamous epithelium into the columnar epithelium with intestine-like features, which is a significant risk factor for the development of esophageal adenocarcinoma." (PMID 38473997, 2024). "Thus, we conclude that Rfx1 expression in the esophageal epithelium is very frequently lost during the progression to esophageal adenocarcinoma, and its loss appears to be a more reliable marker of cancer progression than the up-regulation and then down-regulation of Cdx2." (PMID 21935353, 2011). "Consistent with the current results in gastric adenocarcinomas, gastric intestinal metaplasia and Barrett’s esophagus showed increased expression of HNF4α in conjunction with CDX2." (PMID 39768557, 2024). "For example, cytokine release, triggered by reflux-related inflammation, can lead to the expression of CDX1 and CDX2, intestine-specific factors, in Barrett’s esophagus." (PMID 38473997, 2024). "CDX2 induction is one of the key events in the development of the Barrett’s esophagus to direct intestinal epithelium, while acidic and bile acids are able to increase the Cdx2 promotor activity." (PMID 34199909, 2021). "Animal models in which Cdx2 overexpression is targeted to the esophagus show Barrett’s metaplasia (Barrett’s esophagus), characterized by the presence of intestinal-type epithelia in place of normal squamous epithelia." (PMID 31739541, 2019). "In animal models, a gain of Cdx2 function can elicit a posterior shift in tissue identity, modeling intestinal-type metaplasias of the esophagus (Barrett’s esophagus) and stomach." (PMID 31739541, 2019). "Similar to our results, several studies on Barrett’s esophagus also indicated that CDX2 expression induced by bile acid reflux plays an important role in phenotypic change in the esophageal mucosa." (PMID 30733645, 2019). "Currently, this compound transgenic model (Krt7rtTA; otet-CDX2-T2A-mCherry) represents the best animal model for replicating Barrett’s esophagus." (PMID 31739541, 2019). "Biopsy samples from cases of human Barrett's metaplasia were analysed for the presence of CDX2 and HNF4α." (PMID 27875772, 2017). "In conclusion, our study establishes a role for transcription factors SOX2 and CDX2 in the progression from gastric to gastrointestinal differentiation in Barrett's metaplasia." (PMID 27766003, 2016). "In conclusion, our study establishes a role for the transcription factors SOX2 and CDX2 in the progression from gastric to gastrointestinal differentiation in Barrett's metaplasia." (PMID 27766003, 2016). "We also confirmed that the levels of p27Kip1 and CDX2 were lower in areas of esophageal adenocarcinoma than in those of Barrett's esophagus." (PMID 24765103, 2014). "The initial connection between CDX2 and metaplasia was established by the observation that, intestinal metaplasia of the stomach and Barrett's oesophagus, both express CDX2." (PMID 23828660, 2013). "To determine if a similar approach would yield a novel model for Barrett's esophagus, we subcloned a murine Cdx2 cDNA into a well-established K14/hGH transgenic expression vector (kindly provided by Elaine Fuchs, Rockefeller University)." (PMID 21494671, 2011).
Barrett esophagus (continued). "Cdx2 is ectopically expressed in various pathologic conditions, including Barrett's esophagus and biliary cancer, so understanding its regulation is clinically relevant." (PMID 21935353, 2011). "Since we found that Rfx1 is a negative regulator of the Cdx2 +7 element, we wanted to determine if Rfx1 levels change during the progression from normal human esophageal mucosa to the development of esophageal adenocarcinoma." (PMID 21935353, 2011). "Moreover, CDX2 was down‐regulated by miR‐2116‐3p in Barrett's oesophagus cells treated with omeprazole." (PMID 33621425, 2021). "Moreover, BA has been shown to induce the expression of CDX2 in esophageal epithelial cells and then Barrett's esophagus (BE) cells." (PMID 32705446, 2021). "Here, we sought to characterize SOX2 and CDX2 expression in the distinct morphological steps recognized on the evolutionary phenotype of Barrett's metaplasia and in Barrett's ADC (BA), in an attempt to evaluate their involvement in the differentiation reprogramming of human esophageal mucosa." (PMID 27766003, 2016). "Cdx2, an intestine specific transcription factor, is expressed in Barrett's esophagus (BE)." (PMID 26460825, 2015). "However in Barrett's esophagus with dysplasia and in esophageal adenocarcinoma, the percent of Cdx2 positive cells declined in most samples, but was persistent in others." (PMID 21935353, 2011). "Inappropriate activation of Cdx2 is one of the initiating events in the progression of normal esophageal mucosa to the development of Barrett's esophagus, where esophageal cells form columnar cells that morphologically resemble those of the intestinal epithelium." (PMID 21935353, 2011). "De novo expression of Cdx2 is an early event in the spectrum of the lesions induced by experimental gastro-esophageal reflux and should be considered as a key step in the morphogenesis of esophageal adenocarcinoma." (PMID 19664209, 2009). "CDX2 staining is negative in the normal foveolar mucosa of the stomach in Barrett’s metaplasia, and it was also negative in the normal transitional epithelium in our case." (PMID 39036214, 2024). "Acetylsalicylic acid was shown to inhibit the acid and bile salt induced CDX2 activation and might be therefore a potential drug to prevent the GERD-driven development of Barrett’s esophagus." (PMID 34199909, 2021). "In another study, GS has been shown to suppress bile acid induced caudal type homeobox 2 (CDX2) and cyclooxygenase-2 (COX-2) expression, which are critical in the development of Barrett’s Esophagus and esophageal adenocarcinoma and this effect is due to inhibition of NF-kB activity." (PMID 28261317, 2017). "While Cdx2 is ectopically induced in the early metaplastic condition of Barrett's esophagus, its expression is not necessarily present in progressive Barrett's with dysplasia or adenocarcinoma." (PMID 21935353, 2011). "While these cells were negative for CDX2, results suggested these cells are in a very early stage of the multistep Barrett’s esophagus progression and might be in a stage prior to direct metaplasia in the columnar epithelium." (PMID 30790117, 2019). "Not being present in the normal esophagus, CDX2 expression is a biomarker for Barrett’s esophagus." (PMID 31739541, 2019). "A similar interplay and reciprocal expression of CDX2 and SOX2 is observed in the lower esophagus during progression to the metaplastic epithelium of Barrett’s esophagus and adenocarcinoma, despite the lack of involvement of h." (PMID 40149431, 2025).
gastric adenocarcinoma (25 papers, 2004 to 2025). "CDX2 expression in gastric adenocarcinoma was found to be associated with well‐differentiated tumors (p = 0.027)." (PMID 37602699, 2023). "Our study clarified that loss of CDX2 expression is quite a frequent event in gastric adenocarcinoma." (PMID 37602699, 2023). "Gastric intestinal metaplasia (IM) induced by BAs is a precancerous lesion of gastric adenocarcinoma, which is linked with the expression of caudal-related homeobox 2 (CDX2)." (PMID 35756666, 2022). "We didn't find any association between CDX2 expression and stage of gastric adenocarcinomas." (PMID 22268990, 2012). "The majority of patients in the gastric adenocarcinoma cohort study of TCGA (240 of 440 patients or 54.5%) had an up-regulation of CDX2 (mRNA expression z score compared with normal samples above zero)." (PMID 40149431, 2025). "In the research presented here, the influence of the level of mRNA expression of transcription factor SOX2 in the sub-set of gastric adenocarcinomas with over-expression of CDX2 was examined." (PMID 40149431, 2025). "In this patient, immunohistochemical analysis showed positive expression for CK20, CK7, and CDX-2, strongly supporting the diagnosis of scrotal metastasis from gastric adenocarcinoma." (PMID 40641919, 2025). "To identify the prognostic and predictive value of CDX2 and mucin expression in gastric adenocarcinoma, we prospectively performed CDX2 and mucin protein immunohistochemical staining in a large population sample (n = 782)." (PMID 37602699, 2023). "Taken together, these results suggested that the stromal cells and infiltration of immune cells in gastric adenocarcinoma increased in the CDX2‐low subgroup." (PMID 37602699, 2023). "Final cytological diagnosis of leptomeningeal carcinomatosis due to gastric adenocarcinoma was confirmed by CDX2 immunostaining." (PMID 35183131, 2022). "In this study, we immunohistochemically examined the expressions of GPX1, CDX2, and Ki67 in 172 samples of human gastric adenocarcinomas." (PMID 24228025, 2013). "Our results are entirely consistent with these studies in that CDX2 staining was observed in 61% of gastric adenocarcinomas and significantly favored in the intestinal-type tumors over the diffuse variants (77% versus 45%)." (PMID 22268990, 2012). "The ectopical expression of CDX2 has been reported in intestinal-type gastric adenocarcinomas, and this is consistent with microarray data suggesting that a group of intestine-specific genes are upregulated in gastric adenocarcinomas." (PMID 14710232, 2004). "Conversely, positivity for CK20 and CDX2 supports a diagnosis of gastric adenocarcinoma." (PMID 39713747, 2024). "Biopsy results revealed CDX2-positive cells, indicating gastric adenocarcinoma." (PMID 38361700, 2024). "We showed that gastric adenocarcinoma without CDX2 expression was associated with an increased likelihood of poor differentiation, which is in concordance with several previous studies." (PMID 37602699, 2023). "Furthermore, two investigators scored CDX2 expression independently based on the same criteria in 386 gastric adenocarcinoma samples in the validation cohort." (PMID 37602699, 2023). "CDX2 expression is also observed in intestinal metaplasia and gastric adenocarcinoma." (PMID 30890174, 2019). "Aberrant expression of CDX2 is prominent in intestinal-type gastric adenocarcinoma and CDX-2 may therefore play an important role in gastric carcinogenesis, especially in the intestinal type of GAC." (PMID 24228025, 2013). "CDX2 expression has been documented in gastric adenocarcinoma by several different groups." (PMID 22268990, 2012). "Collectively, the upregulation of two CDX2-dependent genes, CDH17 and DEFA5, found in group 2, represents a characteristic of intestinal cellular lineage that is, in the stomach, implicated in the pathogenesis of intestinal-type gastric adenocarcinoma." (PMID 14710232, 2004).
gastric adenocarcinoma (continued). "Interestingly, Cdx2 transgenic mice develop gastric adenocarcinoma at 100 weeks of age, suggesting that aberrant Cdx2 expression may induce malignant transformation in the stomach." (PMID 28953255, 2017). "The current investigation examines gastric adenocarcinomas that have acquired CDX2 mRNA up-regulation for their concomitant expression of SOX2 and compares CDX2 up-regulated cancers that maintained SOX2 expression with CDX2 up-regulated cancers that have acquired concomitant SOX2 suppression." (PMID 40149431, 2025). "CDX2 and mucin protein expressions were examined and compared with survival and adjuvant chemotherapy benefits in a prospective evaluation cohort of 782 stage II/III gastric adenocarcinoma patients." (PMID 37602699, 2023). "Long-term intestinal metaplasia induced gastric adenocarcinoma in the Cdx2-transgenic mouse stomach and no significant changes were noted in wild-type littermate." (PMID 23181722, 2012).
prostate carcinoma (24 papers, 2008 to 2025). A carcinoma that arises from epithelial cells of the prostate gland. "Since then, others have associated the CDX2 TF-binding site polymorphism with health outcomes as diverse as osteoporosis risk and prostate cancer." (PMID 35065959, 2022). "It was reported that the Cdx2 polymorphism modified the positive association between calcium intake and prostate cancer risk in White and African American people." (PMID 32284510, 2020). "Torkko reported that the Cdx2 polymorphism significantly increased the prostate cancer risk among Hispanic populations carrying the SRD5A2 V89L VV genotype." (PMID 27553621, 2016). "Seven studies involved 4979 cases and 4380 controls related to VDR Cdx2 polymorphism and prostate cancer risk, and 11 studies involved 2837 cases and 2884 controls related to VDR ApaI polymorphism." (PMID 27553621, 2016). "Odds ratios (ORs) and 95 % confidence intervals (CIs) were analyzed to determine the association between VDR Cdx2 and ApaI polymorphisms, and prostate cancer risk." (PMID 27553621, 2016). "The relationship between VDR Cdx2 and ApaI polymorphisms, and prostate cancer risk in previous studies is attributed to differences in lifestyle and disease prevalence as well as limited sample size." (PMID 27553621, 2016). "Environmental interaction with VDR Cdx2 and ApaI polymorphisms and its role in prostate cancer risk needs to be validated." (PMID 27553621, 2016). "The role of VDR Cdx2 and ApaI polymorphisms in prostate cancer was unclear due to ethnic variation in genotypes, controls and subjects, and genotyping techniques." (PMID 27553621, 2016). "Our meta-analysis, including 6427 cases and 6039 controls from 16 case-controlled studies, evaluated the association between Cdx2 and ApaI polymorphisms, and prostate cancer risk." (PMID 27553621, 2016). "We, therefore, investigated the role of VDR Cdx2 and ApaI polymorphisms in prostate cancer risk by conducting a meta-analysis of all the eligible case-controlled studies." (PMID 27553621, 2016). "It has been reported that there is an association between the most commonly recognized polymorphisms in the VDR variants such as Cdx2, Fokl, Bsml, Apal, Taql, and the poly-A microsatellite and prostate cancer." (PMID 24282788, 2013). "The Cdx2 polymorphism has been associated with risk for bone fracture and with risk for prostate cancer in 25(OH)D deficient men; the VDR-5132 polymorphism has been related to risk for prostate cancer." (PMID 18419802, 2008). "Therefore, we conducted a meta-analysis to establish the association between VDR Cdx2 and ApaI polymorphisms, and prostate cancer risk." (PMID 27553621, 2016). "Finally, most studies investigating the VDR Cdx2 polymorphism in prostate cancer risk involved Caucasian population." (PMID 27553621, 2016). "However, studies investigating the relationship between VDR gene polymorphisms (Cdx2 and ApaI) and prostate cancer risk are equivocal." (PMID 27553621, 2016). "VDR Cdx2 AA genotype was associated with prostate cancer in men with low 25(OH)D (≤15 ng/mL) (p interaction = 0.02) and with aggressive and high-grade prostate cancer in men with low 25(OH)D and 1,25(OH)2D (p interaction = 0.04 and 0.01, respectively) compared with men with normal levels." (PMID 25488826, 2015). "While CDX2-positive staining is rare in prostatic cancer, it was relatively common in previously reported MPUAP cases." (PMID 39902031, 2024). "Here we present a case of prostate cancer recurrence found through metastasis to supraclavicular lymph nodes and we also highlight homeobox protein CDX2 as a potential clinico-pathological marker in metastatic prostate cancer." (PMID 36896153, 2023). "FOXA1 is accessible across most prostate cancer cells and CDX2 shows higher accessibility, specifically in one of the Gleason pattern 4 tumours." (PMID 34911933, 2021).
prostate carcinoma (continued). "Among the known VDR polymorphisms, the most common SNPs, influencing the VDR expression in prostate cancer include FokI, BsmI, ApaI, Cdx2, and TaqI." (PMID 27553621, 2016). "Regarding VDR polymorphisms, stronger associations of advanced prostate cancer have been shown with VDR genotypes ff and AA of the polymorphisms FokI and CDX-2 respectively, in the presence of adequate levels of ultraviolet radiation." (PMID 26346690, 2015). "Using this refined IE assay with standardised ICC staining and stringent assessment criteria, CDX2 pCTC was only found in two prostate cancer patients." (PMID 21364588, 2011). "Our findings suggest that VDR Cdx2 and ApaI polymorphisms are not linked to prostate cancer susceptibility in the overall population." (PMID 27553621, 2016). "Evidence failed to support the role of VDR Cdx2 and ApaI polymorphisms in prostate cancer." (PMID 27553621, 2016). "Similarly, ApaI and Cdx2 polymorphisms in prostate cancer risk are not validated." (PMID 27553621, 2016). "CDX2 inhibits the expression of miR-145-5p, thereby relieving the inhibitory effect of miR-145-5p on the translation of SENP1 and affecting the invasion and migration of prostate cancer cells." (PMID 33659248, 2021). "In addition, it is reported in 94% of high-grade prostate carcinomas that having a negative CDX2 would differentiate high-grade prostate carcinoma versus small-cell prostate cancer." (PMID 37185408, 2023). "Prostatic adenocarcinomas with intestinal differentiation had a higher rate of positivity; except for one research work, where a lymph node metastasis and a brain metastasis both exhibited weak (1+) positivity for CDX2, metastatic deposits of prostate cancer have all tested negative for this marker." (PMID 37185408, 2023).